SMIM13 (small integral membrane protein 13)
Synonyms: C6orf228
Tractability: Antibody: UniProt predicts a signal peptide or a membrane-spanning region. PROTAC: its protein half-life has been measured.
Gene: Protein-coding gene on chromosome 6 (11,093,834 to 11,138,733, forward strand). Ensembl gene ENSG00000224531.
Subcellular location: Membrane
Subcellular location (Human Protein Atlas): Nucleoplasm; Golgi apparatus; Nuclear membrane
Gene Ontology:
Cellular component: membrane
Genetic constraint (gnomAD): Loss-of-function variants: 4 observed, 6.61 expected, observed/expected ratio (o/e) 0.61, 90% interval 0.3 to 1.37. That is too few expected variants to judge how well the gene tolerates losing a copy. Missense variants: 85 observed, 104.36 expected, observed/expected ratio (o/e) 0.81, 90% interval 0.68 to 0.98. Synonymous variants: 55 observed, 40.97 expected, observed/expected ratio (o/e) 1.34, 90% interval 1.08 to 1.68.
Homologues: Orthologues: chimpanzee SMIM13 (100% identical), macaque SMIM13 (99% identical), pig SMIM13 (90% identical), dog SMIM13 (89% identical), guinea pig SMIM13 (88% identical), mouse Smim13 (86% identical), rat Smim13 (85% identical), tropical clawed frog smim13 (58% identical), zebrafish smim13 (58% identical).
Diseases named in the same sentence as SMIM13 in open-access papers:
SMIM13 is named in the same sentence as 1 disease in open-access papers, as found by Europe PMC text mining. Sharing a sentence is not in itself a finding about the gene and the disease.
SMIM13 shares sentences with these, for which no sentence is quoted: tumor (1 paper).